LEF1 (lymphoid enhancer binding factor 1)
Diseases named in the same sentence as LEF1 in open-access papers (continued):
Sharing a sentence is not in itself a finding about the gene and the disease.
cancer (continued). "Further investigation is warranted to explore the potential of OTUD7B as a therapeutic target in human cancers by disrupting its interaction with LEF1 and inhibiting Wnt signaling pathway activation." (PMID 37371581, 2023). "A pan-cancer view revealed that LEF1, TCF3,TCF4, and TCF7 have aberrant expression andare potentially involvement in the tumorigenesis of various cancer types." (PMID 38100720, 2023). "Altogether, thisresearch contributes to a more accurate understanding of the expression andclinical and biomarker significance of the LEF1/TCF transcription factors inbreast cancer." (PMID 38100720, 2023). "In summary, the canonical Wnt pathway and LEF1 indicate interplay on several signaling levels and demonstrate that LEF1 plays a crucial role in cancer survival and activity." (PMID 38003292, 2023). "We detected that the majority of those genes are upregulated in cancer areas of the rHGP, thereby suggesting an expression signature associated with WNT signalling via LEF1." (PMID 36691028, 2023). "We found that lymphoid enhancer binding factor 1 (LEF1) had strong enrichment at enhancers compared to NRE in epithelial carcinoma cells." (PMID 37170195, 2023). "The function of 6 NRGs in our signature, including FASLG, IPMK, FLT3, SLC39A7, HSP90AA1, and LEF1, are studied in various cancer types, including BC." (PMID 35864548, 2022). "This study aimed to establish a novel four‐gene signature (CD8A, CD8B, TCF7, and LEF1) to provide a prognostic immunotherapy biomarker for different cancers." (PMID 35588138, 2022). "The induction of T, Eomes, Tbx6 and Lef1, among other genes, points towards increased WNT pathway activity in hypoxia, which was previously observed in cancer cells and linked to EMT." (PMID 36102628, 2022). "Recently, Huang’s group reported a similar study in which they demonstrated that highly cancer-related TF, lymphoid enhancer-binding factor 1 (LEF1), was efficiently degraded by O’PROTACs 29 (DC50 = 25 nM)." (PMID 35813205, 2022). "O’PROTACs were tested on ERG and LEF1, two highly cancer-related transcription factors, and selectively promoted the degradation of these proteins, thereby inhibiting their transcriptional activity in cancer cells." (PMID 35188077, 2022). "Of these DEGs, 6 (EGFR, GATA3, DIABLO, CFLAR, RIPK3, and MAPK8) were repressed, while (ZBP1, PLK1, SPATA2, BCL2, ALK, FASLG, TNFRSF21, and LEF1) were upregulated in cancer cases." (PMID 35610275, 2022). "Lymphoid enhancer binding factor 1 (LEF1) belongs to the LEF/T-cell factor family, and mutations in this gene are found in cancers, especially somatic sebaceous tumor." (PMID 36101745, 2022). "Specifically, LEF1 promotes cancer cell proliferation, viability and EMT, a key characteristic of cancer cell migration and invasion." (PMID 36153326, 2022). "NEO cells from parasympathetic HN-PG expressed NRG3 and LEF1, the latter identified as a cancer checkpoint in HN-PG25." (PMID 36271074, 2022). "Having identified OP‐V1 as a potent LEF1 degrader, we explored the anti‐cancer efficacy of this O'PROTAC." (PMID 34397171, 2021).
cancer (continued). "The four genes are associated with important cancer pathways, namely, the MAPK/PI3K pathways (FN1 and DUSP4), the Wnt pathway (LEF1), and the TGF pathway (SMAD9)." (PMID 34485158, 2021). "An increasing number of studies indicate that LEF1 is essential for invasion, migration, and epithelial-mesenchymal transition in cancer cells." (PMID 34337014, 2021). "Our previous study explicitly elucidated the role of transcriptional factor LEF1 and protein arginine methyltransferase‐1 in the regulation of cancer stem‐like properties and resistance to chemotherapy in esophageal squamous carcinoma cell." (PMID 33463006, 2021). "LEF1 is a transcription factor involved in many cancers, including PCa, and it belongs to the T-cell factor/LEF1 family that regulates gene expression by inducing structural alterations in the DNA helix." (PMID 34868959, 2021). "LEF1 is usually expressed in pre-B and T cells and plays an important role in embryogenesis and cancer development." (PMID 34639214, 2021). "Due to the obvious heterogeneity among these studies (I2 = 80.6%, P=0.000), a random-effects model was used and a significant relationship was observed between elevated LEF1 expression and poor OS of cancer patients (HR = 1.74, 95% CI: 1.06–2.86, P=0.029)." (PMID 32856045, 2020). "Several small molecules have been found to exert anti-cancer effects by suppressing LEF1 and Wnt/β-catenin signaling in multiple cancer types." (PMID 32933177, 2020). "Through RNA sequencing and TruSeq targeted RNA Wnt-signaling panel analysis, we found that the Lef1 gene was significantly upregulated in GC tissues and the expression level of Lef1 was positively correlated with the cancer stage." (PMID 32824603, 2020). "Due to relatively small number of cancer patients in a single study, we performed this meta-analysis based on all current evidence to reach a more reliable conclusion about the prognostic value of LEF1 overexpression in human cancers." (PMID 32856045, 2020). "More high-quality clinical studies are warranted to highlight the prognostic value of LEF1 expression in human cancers." (PMID 32856045, 2020). "In CRC, LEF1 overexpression was positively detected in 44% of cancer patients by TMA analysis and significantly correlated with shorter OS and subsequent occurrence of liver metastasis." (PMID 32856045, 2020). "Hazard ratios (HRs) and 95% confidence intervals (CIs) from the included studies were combined to estimate the effect of LEF1 expression on cancer patients’ survival." (PMID 32856045, 2020). "In conclusion, it was shown by our meta-analysis that elevated LEF1 expression was correlated with poorer OS in patients with various types of cancer, especially solid tumors." (PMID 32856045, 2020). "With respect to a certain cancer type, a significant correlation was identified between LEF1 expression and OS in patients with CRC (HR = 2.15, 95% CI: 1.50–3.07, P=0.000)." (PMID 32856045, 2020). "The oncogenic transcription factor LEF1 as the target gene of miR-34a-5p can also promote malignant lesions via Wnt signal pathway in various cancers." (PMID 32102688, 2020). "In summary, our results demonstrated that PPARγ inhibits the proliferation and metastasis of this malignant tumor by inhibiting LEF1/β-catenin signaling transduction by RT and PPARγ." (PMID 33289586, 2020). "Ten articles reported the impact of LEF1 expression on OS using HRs with 95% CIs in multivariate analysis with a total of 1684 patients diagnosed with human cancers." (PMID 32856045, 2020). "Aberrant LEF1 expression has been discovered in various types of human cancer, and correlated with poor survival." (PMID 32856045, 2020). "A recent review article has highlighted the central role of LEF1 in cancer invasion, migration and proliferation, suggesting its use as a biomarker and potential target for treatments." (PMID 32850701, 2020). "LEF1 knock-down and suppression using shRNA and small molecules decreased cell growth in high LEF1 expressing cancer cells." (PMID 32933177, 2020).
cancer (continued). "LEF1 expression was suggested to serve as a promising biomarker for predicting prognosis in cancer patients." (PMID 32856045, 2020). "We found in this research that LSD1 is capable of enhancing EMT process and BCa cancer progression by complexing with β-catenin to transcriptionally upregulate LEF1." (PMID 32850370, 2020). "In our putative model MYC and LEF1 engage in a positive feedback loop in which oncogenic hits that activate the WNT pathway induce MYC expression in cancer cells." (PMID 31623618, 2019). "This platinated distorted DNA is also a good substrate for other proteins, such as HMG-B4 and other transcription factors containing HMG-boxes such as SRY, LEF-1 or TOX4 that are associated with cancer stemness, and targets for cancer treatment." (PMID 29921764, 2018). "Mechanistically, TCF4/LEF1 forms a complex with β-catenin to bind its target gene promoters and promote cancer cell proliferation." (PMID 29765046, 2018). "OCT4 positively regulated LEF1 expression, and LEF1 mediated the effects of OCT4 in cancer cell EMT, invasion, and migration." (PMID 29974668, 2018). "The present study showed that the overexpression of both OCT4 and LEF1 is an important feature in ESCC progression, and OCT4 is closely correlated with LEF1 expression in the regulation of cancer cell EMT, invasion, and migration." (PMID 29974668, 2018). "We have identified LEF1 as a potential biomarker and therapeutic target for the metastatic phenotype of EBV-associated carcinomas." (PMID 29535816, 2018). "The LEF1 up-regulated genes show comparable levels of expression in cancer cell lines and mesenchymal stem cells, while the LEF1 down-regulated genes show lower expression levels in the cancer cell lines." (PMID 28798381, 2017). "Conversely, the expression levels of transcription factors TCF7L1, TCF7L2 and LEF1 in the Wnt/β-catenin signaling pathway were higher in cancer tissue in both homozygous and heterozygous variation types of the patients." (PMID 29050326, 2017). "We propose that PS-1 is associated with CAJ disassembly and that its enzymatic role contributes to the relocalization of β-catenin from the cell membrane to the nucleus and drives cancer progression by triggering TCF/LEF-1 activation." (PMID 26872378, 2016). "As activation of Wnt pathway is reported to promote EMT in cancer cells, we confirmed this by activating Wnt pathway using LiCl treatment or LEF1 overexpression in HCT116 cells and detected decreased expression of epithelial markers E-cadherin and ZO-1." (PMID 27285761, 2016). "Our current results showing SMA exerted a dose-dependent and strong inhibitory activity against β-catenin-dependent TCF/LEF1 transcriptional activity suggest SMA as an inhibitor against cancer stem cells." (PMID 26544726, 2015). "By contrast, patients with poor clinical outcomes had cancers where LEF-1 expression exhibited varying levels of insensitivity to imatinib." (PMID 25392452, 2014). "Slug (Snail-2) is E-cadherin transcriptional repressor that, together with Snail-1 promotes formation of β-Catenin/TCF4/LEF-1 transcription complexes that initiate EMT in different types of cancers." (PMID 25215932, 2014). "LEF1 codes a 48-kD nuclear protein that is usually expressed in pre-B and T cells and plays an important role in embryogenesis and cancer development." (PMID 24098538, 2013). "Previous studies demonstrated that the expression and activation of LEF1 protein contributed to cancer development." (PMID 24098538, 2013). "The Wnt/β-catenin/LEF-1 pathway plays an important role in cancer stem cell biology, and is required for maintaining properties that regulate self-renewal and differentiation of cancer stem cells." (PMID 22905168, 2012). "To investigate the role of Lef1 in endometrial-gland formation and cancer, we first collected human tissue samples from 133 patients who ranged in age from 26 to 87 years, with a mean age of 64 years." (PMID 22792274, 2012).
cancer (continued). "Through the experiments below we tested the roles of Lef1 in normal development of the endometrial gland, as well as in the emergence of cancer." (PMID 22792274, 2012). "The novel information about the role of Lef1 in angiogenesis improves our understanding as to how the Wnt pathway regulates blood vessel growth both in normal physiological conditions and in cancer." (PMID 22168911, 2011). "Studies have revealed a negative regulatory function of CK1 in the Wnt signaling pathway, where CK1 acts as a negative regulator of the LEF-1/beta-catenin transcription complex, thereby protecting cells from development of cancer." (PMID 17316436, 2007). "Furthermore, we observed a tendency for diminished proliferative capacity of cancer cells and reduced angiogenesis in tumors with LEF1‐depleted 544 cells." (PMID 39887653, 2025). "However, when this pathway is dysregulated, elevated expression of LEF1 can drive cancer initiation and progression." (PMID 40810004, 2025). "Lymphoid Enhancer-Binding Factor 1 (LEF1), has a critical role in the Wnt/β-catenin signaling pathway, which is involved in controlling several cellular functions, including tissue homeostasis, embryonic development, and cancer progression." (PMID 39820173, 2025). "In addition, as a key player of the Wnt/β‐catenin signalling pathway, LEF1 drives the expression of genes involved in tumorigenesis, cancer cell proliferation, stem cell maintenance, embryonic and organ development." (PMID 41208012, 2025). "Considering these previous studies alongside our current work, it is possible that BNP secretion from LEF1‐expressing exp‐CAFs suppresses the formation of rigid extracellular matrix and promotes angiogenesis in xenograft tumors, with cancer cells likely favoring such alternations." (PMID 39887653, 2025). "Although the LEF1 expression may play a role in cancer development, insufficient evidence supports its involvement in malignant phenotype changes." (PMID 39200196, 2024). "Targeting LEF1 IDR to disrupt phase separation may be a feasible strategy for the treatment of cancer." (PMID 37657935, 2023). "Further investigation of LEF1 in the context of cancer progression may contribute to the identification of new therapeutic targets for smart medicine development for CRC patients." (PMID 38003292, 2023). "However, the role of epigenetic modification in LEF1 regulation of cancer progression is poorly understood." (PMID 37553362, 2023). "In one family, the two unaffected family members (Patients 2815 and 2565) harbored a pathogenic variant in LEF1 that was absent in their cancer-affected relatives, suggesting its potential protective role." (PMID 37377903, 2023). "Moreover, it has been verified that miR-34a-5p can directly target LEF1 to act as a cancer suppressor in esophageal squamous cells." (PMID 35340229, 2022). "Interestingly, CD8A, CD8B, TCF7, and LEF1 cannot serve as therapeutic targets for these cancers because of their different expression profiles." (PMID 35588138, 2022). "The results indicated that these TFs—HIF1A, JUN, LEF1, and FOS—were negatively correlated with four glycolysis-associated lncRNAs across the five cancer types, suggesting that the low expression of these lncRNA signatures was accompanied by glycolytic signaling and oncogenic TF activation." (PMID 33627136, 2021). "Lymphoid enhancer‐binding factor 1 (LEF1) is a highly cancer‐related TF." (PMID 34397171, 2021). "The LEF1 protein is essential in uterine glandular formation, and its overexpression possibly influences the disordered growth of glandular cells and the development of cancer." (PMID 34485158, 2021). "LEF1 has been reported as an oncogene in tumors and may play a role in cancer invasion and metastasis." (PMID 34639214, 2021). "Lef1 has also been shown to act independently of β-catenin, both during embryogenesis and cancer." (PMID 32492961, 2020). "In CRC, miR-185 downregulation by TCF1/LEF1 contributed to DC-SIGN-induced cancer metastasis." (PMID 32382150, 2020).
cancer (continued). "Taken together, our results demonstrate that cinobufagin is a promising anti-cancer drug that may be useful for developing targeted therapeutics in LEF1-high expressing cancers." (PMID 32933177, 2020). "Therefore, we conducted this meta-analysis to pool the published estimates and discuss the relationship of LEF1 expression with cancer prognosis." (PMID 32856045, 2020). "Moreover, it was worth mentioning that we unexpectedly learned that Chinese cancer patients with high LEF1 expression had worse OS than those with low expression." (PMID 32856045, 2020). "In the nucleus, LEF1 drives the expression of genes involved in cancer stem cell proliferation." (PMID 32441057, 2020). "Our findings reveal the presence of the DC-SIGN–TCF1/LEF1–miR-185 loop in cancer cells with metastatic traits, implying that it may represent a new pathogenic mechanism of CRC metastasis." (PMID 31217502, 2020). "Through carefully screening the titles and abstracts, 134 articles were discarded for not reporting the association of LEF1 expression with cancer prognosis." (PMID 32856045, 2020). "Evidence suggests that upregulation of transcription factors TCF1 and LEF1 in T-cell and small B-cell lymphoma may confer chemoresistance, suggesting a possibility of reliance on the Wnt pathway for cancer stem cells in lymphoma." (PMID 33126517, 2020). "In light of significance of TGFβ1, SHH, EGFR, and LEF‐1 in the proliferation and migration of cancer cells, we examined the differential expression of those proteins in the cell lysis solution of NFs and CAFs and paid our attention to the different expression of SHH." (PMID 32030915, 2020). "Our findings demonstrate that sebaceous fate during cancer is controlled by Lef1 and Gata6." (PMID 30886049, 2019). "The remaining 28 ‘cancer’ genes identified as upregulated and hypomethylated, as with the acute RE analysis, this included those implicated in TGF-beta signalling (TGFB3, TGFBR2, LEF1 and MECOM) after chronic RE in human skeletal muscle." (PMID 30862794, 2019). "For example, many downstream components of the canonical Wnt signaling pathway are misregulated in a variety of cancers (hepatocellular, colorectal, orapharyngeal squamous cell carcinoma) and their associated metastasis including Axins, β-catenin, and TCF/Lef1 transcription factors." (PMID 30175096, 2018). "Identification of cellular pathways that act downstream of Lef1 in the pLLP may provide clues as to how these factors are misregulated during invasive cancers that show increased Lef1 expression at their leading edge." (PMID 30175096, 2018). "Moreover, the indispensable role of LEF1 in propagating cancerous growth and metastasis also suggests that LEF1 is an ideal target for therapeutic treatment of cancer progression." (PMID 29974668, 2018). "In addition, EBV-associated carcinomas, such as NPC, which are undifferentiated tumors that carry a latent viral infection, have been associated with increased LEF1 and WNT5A mRNA levels." (PMID 29535816, 2018). "These included genes involved in cell death and survival processes (BCLAF1, CFLAR, CASP1, and XIAP), genes associated with proliferation-driving transcription or cancer (KLF4, LEF1, SOX4, ID3), and genes associated with inflammation (CD28, CCR7, CX3CR1 and IFNG)." (PMID 28407008, 2017). "The inhibition of β-catenin/LEF-1 signaling is an emerging strategy in cancer therapy." (PMID 26750754, 2016). "Interestingly, we found that patient CML-6 had the best clinical response to imatinib and was able to achieve a complete cytogenetic response (CCR) within seven months of initiating therapy; LEF-1 expression was markedly inhibited by imatinib in this cancer." (PMID 25392452, 2014). "Expression of lymphoid enhancer factor 1 (LEF1) is frequently altered in different human cancers." (PMID 24098538, 2013). "In summary, our results demonstrated that the balance between the two forms of LEF-1 might have important consequences for normal growth of colon cells and cancer." (PMID 22639890, 2012).